SLC25A1 (solute carrier family 25 member 1)
Diseases named in the same sentence as SLC25A1 in open-access papers (continued):
Sharing a sentence is not in itself a finding about the gene and the disease.
cancer (30 papers, 2016 to 2025). A tumor composed of atypical neoplastic, often pleomorphic cells that invade other tissues. "We next used cBioPortal to explore genetic aberrations of SLC25A1 based on mutation, fusion, amplification, deep deletion, and multiple alternations across 32 types of cancer." (PMID 37981593, 2023). "Especially, SLC25A1 was consistently negatively associated with levels of neutrophils and myeloid dendritic cells across different cancers including PRAD, PAAD, and LUSC." (PMID 37981593, 2023). "SLC25A1 has recently been linked to mitochondrial metabolism due to its ability to increase OXPHOS to prevent cancer cells from apoptosis triggered by energy stress." (PMID 37741815, 2023). "Meanwhile, the associations of SLC25A1 with prognostic value, molecular pathways, immune infiltration, and other immune-related biomarkers in pan-cancer were also explored based on online bioinformatics tools and R program." (PMID 37981593, 2023). "Slc25a1 activity has been linked to several pathologic conditions including cancer, aging, and developmental disorders." (PMID 35585086, 2022). "In our hand, inhibition of the mitochondrial citrate transport protein (SLC25A1) enhanced radiosensitivity of cancer cells and this was associated with increased levels of D-2-HG and a delayed repair of radiation-induced DNA damage." (PMID 35869047, 2022). "We have recently discovered that cancer cells are able to take up citrate through the plasma membrane variant (pmCiC) of the mitochondrial (mCiC) citrate carrier (SLC25A1) belonging to the SLC25 gene family." (PMID 33425906, 2020). "Aberrant SLC25A1 activity or expression has been implicated in various diseases, particularly cancer, where it supports cancer cell growth and resistance to energy stress-induced apoptosis by enhancing lipogenesis and upregulating oxidative phosphorylation (OXPHOS)." (PMID 39881208, 2025). "Furthermore, amplifications of the SLC25A1 gene or enhanced transcription rates are a hallmark of several cancer types as well as of metabolic disorders." (PMID 33499062, 2021). "Moreover, knockout of SLC25A1 has been associated with dysregulation of mitochondrial metabolism in cancer cells." (PMID 29888201, 2018). "Since SLC25A1 has recently been linked to cellular redox homeostasis we wondered whether SLC25A1 might contribute to increased radioresistance of cancer cells in acute or chronic cycling severe hypoxia." (PMID 29888201, 2018). "Further linking the inhibition of the SLC25A1/ACLY-FSP1 pathway to cancer, we investigated the effect of BTA or SB204990 on tumor sensitivity to ferroptosis in the A375 xenograft model." (PMID 39881208, 2025). "Inhibition of SLC25A1 or ACLY leads to impaired cancer cell proliferation, differentiation, and sensitization to immune therapy, highlighting their role as potential effective targets for anti-cancer strategy." (PMID 39881208, 2025). "Targeting the SLC25A1-ACLY axis is therefore a potential therapeutic strategy for ferroptosis-targeted cancer intervention." (PMID 39881208, 2025). "Here, we use a targeted CRISPR-Cas9 screen of the SLC superfamily to identify SLC25A1 as a critical ferroptosis regulator in human cancer cells." (PMID 39881208, 2025). "Proteomics analysis from the Cancer Cell Line Encyclopedia revealed a positive correlation between SLC25A1 and FSP1 expression." (PMID 39881208, 2025). "Pharmacological inhibition of SLC25A1 and ACLY significantly enhances cancer cell susceptibility to ferroptosis both in vitro and in vivo." (PMID 39881208, 2025). "Taken together, these analyses indicate the clinical significance of SLC25A1-ACLY axis in prognosis of cancer patients." (PMID 39881208, 2025).
cancer (continued). "Despite the precise role of D-2-hydroxyglutarate in cancer cell damage, the inhibition of SLC25A1 has a supportive effect on radiation therapy." (PMID 40722961, 2025). "The co-administration of ionizing radiation with an SLC25A1 inhibitor effectively overcomes the enhanced radioresistance of cancer cells." (PMID 40722961, 2025). "A growing body of research investigated the effects of the genetic suppression or pharmacologic inhibition of SLC25A1 alone and in combinatorial therapies on cancers in vitro and in vivo." (PMID 37981593, 2023). "Our findings suggest the potential of SLC25A1 as a prognostic biomarker for cancers and a therapeutic target for precise antitumor strategy and cancer immunotherapy." (PMID 37981593, 2023). "We also explored the correlation between SLC25A1 expression and the pathological stages of cancers using TCGA data." (PMID 37981593, 2023). "Past research has shed light on the critical role of SLC25A1 in the prognosis and therapy of various human cancers." (PMID 37981593, 2023). "Then, we studied the top 100 genes positively correlated with SLC25A1 expression in pan-cancer of TCGA with the GEPIA2 tool." (PMID 37981593, 2023). "Previous research has demonstrated that SLC25A1 increased OXPHOS to prevent cancer cells from apoptosis triggered by energy stress." (PMID 37741815, 2023). "Our analysis is the first comprehensive study of the expression levels, clinical prognosis, as well as its immunological and biological implications of SLC25A1 on a pan-cancer basis." (PMID 37981593, 2023). "The expression of SLC25A1 mRNA between normal tissues and tumors in pan-cancer was investigated by combining GTEx and TCGA data." (PMID 37981593, 2023). "We aim to analyze the expression profile, prognostic value, potential immunological significance, and effect on tumor growth of SLC25A1 at a pan-cancer level." (PMID 37981593, 2023). "The cancer dependency screens showed that the majority of cancer cell lines display varying degrees of reliance on SLC25A1." (PMID 37981593, 2023). "Abnormal expression or activity of SLC25A1 has been found to be involved in inflammation, cancer, and other diseases." (PMID 37981593, 2023). "To further study the expression of SLC25A1, we performed immunohistochemical staining (IHC) in tissue microarrays containing several kinds of human normal tissues and cancers." (PMID 37981593, 2023). "In this report, we first analyzed the impacts of SLC25A1 genetic inhibition by CRISPR/Cas9 at the pan-cancer level via the Dependency Map (DepMap) project." (PMID 37981593, 2023). "Although the SLC25A1 expression across various cancers was investigated using public databases and immunohistochemistry, the sample size of tissue microarray in this study was small, resulting in limited information." (PMID 37981593, 2023). "Several lines of evidence have demonstrated that SLC25A1 enhances cancer growth by promoting mitochondrial oxidative metabolism and de novo lipid synthesis." (PMID 37981593, 2023). "The findings of this study offer a basis for understanding the roles and potential mechanisms of SLC25A1 in human tumors, and provide a novel perspective for the application of SLC25A1 in cancer therapy." (PMID 37981593, 2023). "SLC25A1 has been extensively investigated in relation to cancer, and abnormal expression of SLC25A1 promotes the growth and invasion of cancer cells through metabolic regulation, making it a potentially effective treatment." (PMID 37741815, 2023). "Meanwhile, the area under the curve (AUC) values for ROC analysis of SLC25A1 mRNA expression was performed in each cancer." (PMID 37981593, 2023). "The increased oxidative phosphorylation (OXPHOS) induced by SLC25A1 supports the resistance and adaptation of cancer cells to radiotherapy, platinum-derived agents, and other metabolic and respiration stress conditions." (PMID 37981593, 2023).
cancer (continued). "In the present study we further validated the induction of D-2-HG by SLC25A1 inhibition in additional cancer cell lines by applying genetic inhibition using RNAi technology and a novel, 3rd generation small molecule inhibitor of SLC25A1, CTPI2." (PMID 35869047, 2022). "Here we aimed to explore the suggested contribution of D-2-HG-accumulation to disturbance of DNA repair, presumably homologous recombination (HR) repair, and enhanced radiosensitivity of cancer cells with impaired SLC25A1 function." (PMID 35869047, 2022). "We concluded that SLC25A1 inhibition affects the repair of IR-induced lethal DNA lesions by inducing D-2-HG accumulation and thereby sensitizes cancer cells to PARPi in combination with IR in vitro and in vivo." (PMID 35869047, 2022). "Altogether these findings support a crucial role of SLC25A1 for cancer cell proliferation and survival." (PMID 35869047, 2022). "The CTPI2-induced impairment of Rad51 foci resolution in irradiated cancer cells corroborate a disturbance of HR repair by SLC25A1 inhibition." (PMID 35869047, 2022). "In summary, D-2-HG induction by genetic or pharmacologic inhibition of SLC25A1 or direct treatment with octyl-D-2-HG impact cellular processes which are important for the survival of irradiated cancer cells." (PMID 35869047, 2022). "The mechanisms of SLC25A1 in cancer referred to its antioxidant defense and maintenance of the self-renewal capability of cancer stem cells." (PMID 32802843, 2020). "The mitochondrial citrate carrier, Slc25a1, (or CIC) belongs to a family of ion transporters whose activity has been linked to several pathologic conditions including cancer, aging, and developmental disorders." (PMID 31959914, 2020). "In line with this, we found downmodulation of the primary prostatic citrate transporters, SLC25A1, remarkable since its involvement in cancer therapy resistance and stemness." (PMID 33375130, 2020). "We show that SLC25A1 can contribute to the increased antioxidant defense of cancer cells allowing them to escape the cytotoxic effects of IR." (PMID 29888201, 2018). "This further corroborates our assumption that chronic cycling hypoxia/reoxygenation stress increases not only the expression but also the reliance of cancer cells on the SLC25A1 mediated redox-homeostasis for survival under stress conditions." (PMID 29888201, 2018). "Overall, SLC25A1 is important for the maintenance of mitochondrial homeostasis and its overexpression was shown to drive tumorigenesis in various types of cancer." (PMID 29888201, 2018). "Taken together, we identified a role of SLC25A1-regulated redox homeostasis in the tolerance of cancer cells to acute and chronic cycling hypoxia and increased radioresistance caused by adaptation to these stress conditions." (PMID 29888201, 2018). "Increased levels of CiC have been found in human cancers, while inhibition of CiC activity showed anti-tumor activity, and SLC25A1 gene has been implied in epigenetic regulation or cancer biology." (PMID 27231907, 2016). "Conversely, SLC25A1 overexpression has been observed in patients with malignant tumors." (PMID 40722961, 2025). "SLC25A1 is involved in the mitochondrial citrate pool and redox homeostasis in cancer stem cells." (PMID 40722961, 2025). "It has been reported that SLC25A1 promotes cancer cell survival and growth." (PMID 39881208, 2025). "Previously, it has been suggested that SLC25A1 acts as a metabolic oncogene, although its significance in cancer treatment remains unclear." (PMID 39329971, 2024). "Furthermore, genetic suppression or pharmacologic inhibition of SLC25A1 significantly inhibited tumor growth and metastasis in a variety of common human cancer cell lines, whereas SLC25A1 overexpression enhanced the malignant phenotype." (PMID 37981593, 2023). "Our study indicates that the prognostic significance of SLC25A1 varies across different cancers." (PMID 37981593, 2023).
cancer (continued). "Importantly, the prognostic significance, immunological role, and biological effects of SLC25A1 in cancers require follow-up appropriate models in vitro or in vivo and large clinical samples to testify." (PMID 37981593, 2023). "However, the landscape of SLC25A1 gene expression and its biological function in different types of human cancers remains elusive." (PMID 37981593, 2023). "Co-dependencies of SLC25A1 in cancer were also examined using the DepMap data." (PMID 37981593, 2023). "Therefore, we mainly focused on exploring the expression level and significance of SLC25A1 across human pan-cancers in the following analysis." (PMID 37981593, 2023). "Hence, SLC25A1 has been proposed to be a novel therapeutic target in cancer, which spurred the development of selective SLC25A1 inhibitors such as BTA, CTPI-1, and CTPI-2." (PMID 37981593, 2023). "Furthermore, the knockout of SLC25A1 demonstrated inhibitory effects in most cancer cell lines in the DepMap project." (PMID 37981593, 2023). "We examined the prognostic values of SLC25A1 across 33 cancer types in the TCGA database." (PMID 37981593, 2023). "In order to comprehensively study SLC25A1 expression on cancer cell growth, we analyzed the vulnerability to CRISPR/Cas9-mediated perturbation of SLC25A1 in large panels of human cancer cell lines using the DepMap project data (DepMap 22Q2 Public + Score, Chronos)." (PMID 37981593, 2023). "Future functional studies and independent validation will help to determine whether SLC25A1 can be used as an independent predictive factor in cancers." (PMID 37981593, 2023). "For example, there was an increase in the methylation of an immunologic marker gene CD79A, a decrease in methylation of a tumorigenic modulation gene DICER1, and a decrease in methylation of SLC25A1, a critical gene in mitochondrial homeostasis that is highly upregulated in cancer." (PMID 37138315, 2023). "Deep studies focusing on the functions of SLC25A1 in oncogenesis may facilitate the discovery of new prognostic biomarkers and the development of effective targets for cancer treatment." (PMID 37981593, 2023). "First, we investigated if we could reproduce our earlier findings on the link between SLC25A1 inhibition and D-2-HG accumulation in other cancer cells." (PMID 35869047, 2022). "However, the functional roles of SLC25A1, the only known transporter of human citrate, in the regulation of lipid metabolism remains unexplored in human cancer cells, including CRC." (PMID 34839347, 2021). "In addition, Slc25a1 promotes the expansion of cancer stem cells and the progenitor stem cell population in the liver is proposed to play an important role in the development of HCC." (PMID 31959914, 2020). "Notably, pharmacological inhibition of SLC25A1 sensitizes cancer cells to ionizing radiation, cisplatin or EGFR inhibitor treatments in lung cancer." (PMID 32103057, 2020). "Several evidences implicate that SLC25A1 plays a role in cancer progression." (PMID 32265986, 2020). "Moreover, exposure to IR, acute hypoxia, and chronic cycling severe hypoxia increased SLC25A1 expression in our in vitro models of anoxia-tolerant cancer cells." (PMID 29888201, 2018). "Thereby our data confirm the assumption that SLC25A1 might be crucial for metabolic plasticity of cancer cells enabling adaptation and survival under adverse conditions such as nutrient starvation (glucose) or oxidative stress suggested by others." (PMID 29888201, 2018). "It appears that inhibition of SLC25A1 leads to a massive disturbance of mitochondrial metabolism and this might severely affect the ability of cancer cells to cope with the toxic effects of IR leading to radiosensitization and enhanced clonogenic cell death." (PMID 29888201, 2018). "As CSCs are the source of cancer initiation, we asked whether SLC25A1 affects the expansion of this population." (PMID 29651165, 2018).
cancer (continued). "Here, we explored the role of the mitochondrial citrate carrier (SLC25A1) for the improved antioxidant defense of cancer cells with tolerance to acute and chronic severe hypoxia/reoxygenation stress and the use of pharmacologic SLC25A1 inhibition for tumor cell radiosensitization." (PMID 29888201, 2018). "Previously, we proposed that SLC25A1 is a metabolic oncogene, but its importance in cancer therapy is still unknown." (PMID 29651165, 2018). "Collectively, the modulation of SLC25A1 could be a potential therapeutic strategy against cancer." (PMID 40722961, 2025). "Therefore, our findings propose that the SLC25A1-ACLY pathway could be targeted to leverage ferroptosis for therapeutic intervention in cancer." (PMID 39881208, 2025). "Thus, the inhibition of SLC25A1 induces the dysregulated self-renewal of cancer stem cells." (PMID 40722961, 2025). "Interestingly, the SLC25A1 knockdown alone induced cell death and increased lipid ROS levels, implying that SLC25A1 may directly induce ferroptosis in cancer cells." (PMID 39881208, 2025). "Interestingly, our previous work revealed a strategy to induce 2-HG accumulation as a common phenotype by inhibiting the mitochondrial citrate carrier SLC25A1 in cancer cells without somatic mutation of IDH." (PMID 38225236, 2024). "Given that increased exogenous fatty acid (FA) uptake, another well characterized lipid metabolism alteration in human cancers, may also contribute to SLC25A1-induced accumulation of lipid content, we further evaluated the effect of SLC25A1 downregulation or upregulation on FA uptake in CRC cells." (PMID 34839347, 2021). "Importantly, the enhanced flexibility of mitochondrial metabolism as a consequence of upregulated SLC25A1 expression might contribute to increased stress-tolerance of the NCI-H460 cancer cells." (PMID 29888201, 2018). "Since upregulation of SLC25A1 is induced by adverse conditions in the tumor environment, exposure to IR, or both pharmacologic inhibition of SLC25A1 might be an effective strategy for radiosensitization of cancer cells particularly in chronically hypoxic tumor fractions." (PMID 29888201, 2018). "Interestingly, treatment with BTA or CNASB particularly lowered the spare respiratory capacity of anoxia-tolerant NCI-H460 cancer cells, pointing to a possible involvement of SLC25A1 in adaptation of oxidative metabolism to metabolic stress induced by chronic cycling severe hypoxia." (PMID 29888201, 2018). "KEGG pathway analysis revealed that SLC25A1 knockdown significantly upregulated several inflammatory and immune pathways, including TNF, IL-17, NK cell-mediated cytotoxicity, which inhibit cancer development." (PMID 39881208, 2025). "SLC25A1 and ACLY support rapid cell proliferation and epithelial-mesenchymal transition and maintain cancer stem cell stemness by upregulating fatty acid synthesis and histone acetylation." (PMID 39881208, 2025). "The correlation between SLC25A1 expression and CD4 + T cells, CD8 + T cells, neutrophils, myeloid dendritic cells, macrophage, and B cells was systematically evaluated at the pan-cancer level in this study." (PMID 37981593, 2023). "Our study showed that SLC25A1 expression was positively related to MSI in 9 cancers and TMB in 6 cancers." (PMID 37981593, 2023). "Blocking of the citrate transport from mitochondria into the cytoplasm with an SLC25A1 inhibitor, benzenetricarboxylate (BTA), had several effects on cancer cells including increased glycolysis, ROS synthesis, mitophagy and disrupted mitochondrial homeostasis." (PMID 33425906, 2020). "Our results revealed that treatment with the SLC25A1-inhibitor BTA sensitized both oxic and anoxia-tolerant NCI-H460 cancer cells to the cytotoxic action of IR when treatment was performed under Nx conditions." (PMID 29888201, 2018).